STAT3 (signal transducer and activator of transcription 3)
Diseases named in the same sentence as STAT3 in open-access papers (continued):
Sharing a sentence is not in itself a finding about the gene and the disease.
cancer (continued). "IL-6 and STAT3, in particular, have been experimentally linked to fatigue in cancer patients due to their roles in cytokine signaling and mitochondrial dysfunction." (PMID 40435272, 2025). "Dysregulated activation of STAT3 has been directly linked to various human cancers, making it a significant target for cancer therapy." (PMID 39786519, 2025). "As a transcription factor, STAT3 regulates a series of genes associated with biological processes such as cancer cell hyperproliferation, invasion and metastasis, and immune evasion." (PMID 40740310, 2025). "Restoring PDLIM2 expression can also suppress p65 and STAT3 activity enhance the expression of genes involved in antigen presentation and T cell activation, and inhibit cancer-related genes, thereby rendering cancer cells more susceptible to immune attack." (PMID 40476213, 2025). "Seven genes have been found by the STAT family; STAT3 in particular is generally thought to be linked to metastasis, cancer growth, and multidrug resistance." (PMID 40052129, 2025). "Background/Objectives: Signal Transducer and Activator of Transcription 3 (STAT3) is a transcription factor that is strongly implicated in various cancers." (PMID 40075607, 2025). "Mechanistically, the combined loss of mutant KRAS and STAT3 disrupts a core transcriptional program of cancer cells critical to oncogenic competence." (PMID 40859018, 2025). "Consistently, previous studies have established that STAT3 activation is responsible for ANGPTL4 expression in cancer-associated fibroblasts (CAFs)." (PMID 40616161, 2025). "Among these, STAT3 has been particularly implicated in fibroblast activation and the maintenance of a cancer-associated phenotype." (PMID 40472740, 2025). "STAT3 responds to IL-6 family cytokines and regulates inflammation, cell survival, and immune tolerance; dysregulated STAT3 signaling is implicated in both cancer and chronic infection." (PMID 41009690, 2025). "Bidirectional communication between cancer stem cells (CSCs) and cancer-associated fibroblasts (CAFs) amplifies stemness via paracrine stimulation of the IL-6/STAT3, TGF-β/SMAD, and CXCL12/CXCR4 signaling pathways." (PMID 41439922, 2025). "A study indicated that chronic inflammation is associated with cancer because crucial risk factors can activate proinflammatory transcription factors, such as NF-κB and STAT3." (PMID 40061959, 2025). "Among these, the transcription factors STAT3 and nuclear factor kappa-light-chain-enhancer of activated B cells (NF-κB) are pivotal in associating inflammation with cancer." (PMID 40420174, 2025). "STAT3: since inhibiting STAT3 in tumors with constitutively active STAT3 has been shown to cause cell death, STAT3 is increasingly being studied in relation to anti-cancer treatment." (PMID 40227591, 2025). "Conversely, other research indicates that activation of the JAK2/STAT3 pathway, mediated by IL‐6, can lead to muscle atrophy, with STAT3 inhibition mitigating muscle wasting caused by cancer cachexia." (PMID 39764565, 2025). "Overexpression of activated STAT3 is associated with an unfavorable prognosis in different types of cancer." (PMID 40860906, 2025). "Constitutive activation of STAT3 (pSTAT3), a hallmark of many cancers, is driven by persistent exposure to cytokines such as IL-6, IL-10, and oncostatin M, leading to continuous phosphorylation and nuclear translocation of STAT3." (PMID 41463071, 2025). "As a general rule, when STAT3 is activated in cancer cells, it causes a change in the function of proteins that regulate and control the expression of inflammation genes by affecting the function of secretory proteins." (PMID 40092547, 2025).
cancer (continued). "The treatment also reduced the levels of molecules linked to inflammation and cancer progression, such as IL-6 and STAT3, and disrupted the internal skeleton that helps cells divide and spread." (PMID 41514893, 2025). "The integration of these inflammatory, catabolic, and metabolic pathways underscores STAT3’s pivotal role in the rapid loss of muscle mass and function characteristic of advanced cancer cachexia." (PMID 40704145, 2025). "Since STAT3-mediated regulation of cathepsin-B has been implicated in ferroptosis of cancer cells, we next investigated their roles in HT22 neuronal ferroptosis and the action of 8-HANQ." (PMID 41304754, 2025). "Recent studies have linked cancer progression to the reduced ubiquitination and subsequent over‐expression of STAT3,23, 24, 49 identifying it as a potential therapeutic target for some malignancies." (PMID 39936533, 2025). "Both NF-κB and signal transducer and activator of transcription 3 (STAT3), which have been linked to the development of cancer, have been demonstrated to be activated by these cytokines." (PMID 39812539, 2025). "In ATC, resistance to doxorubicin (DOX) has been linked to signal transducer and activator of transcription 3 (STAT3)-mediated enhancement of cancer stem cell characteristics via INO80 regulation." (PMID 40843353, 2025). "Chronic inflammation and cancer are intricately linked, driven by common signaling pathways such as NF‐kB, STAT3, and mTOR, which regulate proinflammatory cytokine production, creating a self‐sustaining feedback loop." (PMID 40387308, 2025). "Expectedly, the levels of M2 macrophage-related markers Arg1, p-AMPK, and p-STAT3 showed a tendency to decrease in IDH2-deficient macrophages co-cultured with cancer cells." (PMID 39256649, 2024). "Cancer-associated fibroblasts (CAF) derived IL6 induced the differentiation of CD73+γδTreg in normal breast tissue through IL6/STAT3 pathway." (PMID 39188712, 2024). "Activation of IL6 through STAT3 (signal transducer and activator of transcription 3) in cancer-associated fibroblasts (CAF) has been shown to enhance the resistance of CCA to gemcitabine." (PMID 38672199, 2024). "GSEA further revealed a significant correlation between SPOP loss and STAT3 activation, which is involved in both cancer stemness and immune regulation." (PMID 39479456, 2024). "And RTKs-JAKs-STAT3 signaling are well-elucidated signaling networks in cancers involving almost all cancer hallmark features." (PMID 38245798, 2024). "In various cancers, an association between signal transducer and activator of transcription 3 (STAT3), interleukin 6 (IL6), and epidermal growth factor receptor (EGFR) on PD-L1 expression has been shown in varying degrees." (PMID 38434518, 2024). "For example, the activation of STAT3 is closely linked to the occurrence of multiple tumors, the formation of drug resistance, and the maintenance of cancer stem cells." (PMID 39355266, 2024). "In cancer, STAT3 is frequently hyperactive due to upstream mutations or elevated cytokine levels in the tumor microenvironment, driving oncogenesis and metastasis." (PMID 39597836, 2024). "STAT3 is constitutively activated in many cancers, and TAMs cause STAT3-dependent expression of proangiogenic molecules leading to stimulating STAT3 action in ECs, thereby promoting vascularization." (PMID 39003350, 2024). "Increased import of STAT3 in the nucleus has been implicated in cancers as it activates genes specific to cell cycle progression, EMT, and survival." (PMID 38519574, 2024). "STAT3 functions as a crossroad for multiple cancer-causing signaling pathways and controls the immune reaction to tumors." (PMID 38633613, 2024). "Another report demonstrates that cancer-associated fibroblast-derived IL-6 increased c-Met expression in MET-unamplified GC cells through the IL-6/IL-6R/JAK2/STAT3 signalling pathway." (PMID 37950040, 2024).
cancer (continued). "Recently, active STING signaling has been linked to the survival of chromosomally unstable cancers in an IL-6 dependent manner involving both NF-κB and signal transducer and activator of transcription 3 (STAT3) activation." (PMID 38660307, 2024). "The IL-6/JAK/STAT3 pathway is aberrantly hyperactivated in many types of cancers and is generally associated with a poor clinical prognosis." (PMID 39247610, 2024). "The ERK, MYC, and STAT3 signaling pathways have all been implicated in the activation of EZH2 in different types of cancer, including hematopoietic malignancies." (PMID 38339397, 2024). "It is well-accepted that VEGFR/STAT3 signaling is implicated in angiogenesis in a variety of cancers." (PMID 38918360, 2024). "STAT3 activation in cancers is rarely due to mutations and mainly relies on post-translational modifications." (PMID 39769907, 2024). "Phosphorylated STAT3 (p-STAT3) is known to be activated in various cancers, including CRC, and has been associated with patient survival and response to chemotherapy." (PMID 39000577, 2024). "Exosomal miR-21, derived from cancer associated fibroblasts, was shown also to activate STAT3 and promote cisplatin resistance in oesophageal squamous cell carcinoma." (PMID 39285292, 2024). "Our previous results showed that MAPKi promote feedback activation of STAT3 signaling in BRAF-mutated cancer cells." (PMID 38822350, 2024). "As the rapid advances in exosome mediates biological activities, many studies suggest that exosome tightly crosstalk with STAT3-mediated cancer hallmark features." (PMID 38245798, 2024). "Silencing of SOCS3 causes decreased inactivation of STAT3, which also contributes to its constitutive activation and, thus, the progression of cancers such as hepatocellular carcinoma and cholangiocarcinoma in both cell and animal models." (PMID 38611065, 2024). "Research showed that STAT3 plays an important role in regulating the expression of genes associated with various types of cancer." (PMID 39153914, 2024). "Dysregulated STAT3 signaling has been implicated in various disease conditions, including cancers, autoimmune disorders, and kidney diseases." (PMID 39335615, 2024). "The main mechanisms of STAT3 in regulation of chemoresistance are due to the extensive cancer hallmark features of STAT3, the feedback loops or altered crosstalk between STAT3 and other signaling pathways." (PMID 38245798, 2024). "When Akt is inhibited in PTEN-deficient cancer cells, there can be a large increase in STAT3 signalling that compensates." (PMID 38785562, 2024). "Within the STAT family, STAT3 is particularly crucial in regulating gene expression associated with cancer progression." (PMID 39139281, 2024). "One of the most important oncogenic transcription factors engaged in a regulation of the signaling pathway associated with cancer is signal transducer and activator of transcription 3 (STAT3)." (PMID 39305962, 2024). "In cancer studies, overexpressed STAT3 has been associated with IL-6–induced MMP9 release, which favors invasiveness/metastasis." (PMID 37982695, 2024). "This suggests that exosomal LINC00691 promoted NFs to gained the properties of cancer-associated fibroblasts (CAFs) depending on JAK2/STAT3 signaling pathway as a potential diagnostic biomarker for GC." (PMID 39703839, 2024). "Elevated STAT3 activity induces resistance in PTEN-deficient cancer cells to PI3K/AKT/mTOR inhibitors." (PMID 39309860, 2024). "Elevated EGFR levels activate several downstream signaling pathways, including STAT3, which is hyperactivated in these cancers and associated with increased cell proliferation and poor prognosis." (PMID 39123466, 2024). "The JAK2/STAT3 signaling pathway is implicated in various physiological and pathological processes, including cancer, inflammation, and tissue injury." (PMID 38787114, 2024).
cancer (continued). "This profiling includes the analysis of activated forms of STAT3 (Y705 phospho-STAT3) and the expression levels of downstream targets associated with cancer cell proliferation and survival." (PMID 40836974, 2024). "Conversely, STAT3 activation is typically associated with autocrine stimulatory loops in cancer, providing a growth advantage to the cells." (PMID 39200479, 2024). "Studies have shown that metformin specifically inhibits the nuclear translocation of NF-κB and the phosphorylation of STAT3, thereby suppressing the inflammatory response associated with the growth of cancer stem cells (CSCs) and cellular transformation." (PMID 38612893, 2024). "TQ also modulates the NF-κB and STAT3 pathways, both of which are implicated in cancer progression and survival." (PMID 39769996, 2024). "Members of the STAT family are thought to be implicated in the development of human cancers and STAT3 and STAT5 are considered to be carcinogens with important implications for cancer biology." (PMID 38294290, 2024). "Suppressing the signal transduction of STAT3 causes a decrease in the expression of survivin, which in turn makes it possible to stimulate apoptosis in cancer cells." (PMID 38238515, 2024). "As part of the STAT family, STAT3 has been discovered to be implicated in a variety of disorders, such as cancer, where STAT3 is highly expressed and persistently activated, encouraging the growth and proliferation of tumors." (PMID 38419883, 2024). "In several cancer subsets, induction of oncogenic STAT3 associates with increased expression of FGFR4, a member of a tyrosine kinase family of FGFRs involved in cell growth, differentiation and migration." (PMID 37945798, 2024). "The hyperactivation of the STAT3 signaling pathway has been detected in a multitude of cancer types, where it has been associated with poor clinical outcomes." (PMID 39001513, 2024). "Of these, STAT3 is notably implicated in cancer pathogenesis and is a key player in macrophage M2 polarization, alongside STAT6." (PMID 38747738, 2024). "By selectively inhibiting STAT3, these drugs have the potential to cause less damage to healthy cells while effectively targeting cancer cells." (PMID 38892287, 2024). "CD44, a receptor for hyaluronic acid, is a cancer stem cell marker frequently associated with chemoresistance that can activate STAT3." (PMID 39131380, 2024). "In the early stages of cancer, the STAT3 pathways participate in several tissues, which are linked with cancer growth upregulating cell stemness and proliferation." (PMID 39188680, 2024). "STAT3 can control the expression of genes linked to cancer development, and its chronic activation has been extensively studied in various human cancers." (PMID 38397437, 2024). "As a latent transcription factor, STAT3 regulates a set of genes implicated in cancer cell survival, proliferation, angiogenesis, invasion, and metastasis." (PMID 38166947, 2024). "Some previous studies also support the critical role of phospho-STAT3(Tyr705) in the tumorigenic features of IDH mutated cancer." (PMID 38347540, 2024). "This variant-specific modulation of STAT3 signaling by LOC344887 is a novel finding that imposes significant implications for deeper understanding the functional diversity of lncRNAs in cancer." (PMID 39664573, 2024). "Large granular lymphocyte (LGL) leukemia is a rare hematologic malignancy characterized by clonal expansion of cytotoxic T-cells frequent somatic activating STAT3 mutations." (PMID 39497832, 2024). "The JAK2/STAT3 signalling pathway is closely associated with the occurrence and development of many diseases, particularly cancer." (PMID 38879667, 2024).
cancer (continued). "While the involvement of STAT3 in cancer has been predominantly associated with chronic inflammation and fibrosis, our data underscore the significance of epistasis as a key factor that underlies functional antagonism between STAT3 and TGF-β/SMAD4 signaling." (PMID 38573819, 2024). "In the same vein, interventions against the PI3K/Akt/mTOR and JAK/STAT3 pathways, linked to cancer progression and metastasis, are pursued to dampen CSC proliferation and stemness." (PMID 38673727, 2024). "Meanwhile, the IL-6/JAK/ STAT3 Signaling pathway is overactivated in many forms of cancer, and it is implicated in driving cancer cell proliferation, invasion, and metastasis, as well as interacting with TIME to inhibit antitumor immune responses." (PMID 36949898, 2023). "A study of cancer-associated fibroblasts found increased phosphorylation of STAT3 to correlate with decreased overall survival in sCRC, with implications for CAC." (PMID 37884500, 2023). "These traits together with the phenotypic effects described in our cell models strongly suggest that low STAT3 phosphorylation levels must be associated with a better cancer prognosis." (PMID 37945711, 2023). "IL-6 acts directly on cancer cells to induce the expression of STAT3-encoding proteins driving cancer proliferation, i.e., cyclin D1 and survival, i.e., BCL2-like protein 1 (BCL-xL)." (PMID 37480115, 2023). "In contrast, in the presence of Dox, expression of these markers was reduced, indicating STAT3 is essential for MB sphere formation and the expression of genes associated with cancer stem cells." (PMID 37190167, 2023). "Studies have found that the activation of STAT3 signaling pathway is associated with skeletal muscle atrophy during burn, cancer and degenerative muscle diseases." (PMID 37090725, 2023). "Overexpression of STAT3 is strongly associated with cancer cell survival, proliferation, invasion, metastasis, drug resistance, and immune evasion, among other related genes." (PMID 36733714, 2023). "The JAK/STAT3 pathway is aberrantly over-activated in many types of cancer and this over-activation is often associated with a poor clinical prognosis." (PMID 37270563, 2023). "A separate study similarly identified a population of inflammation-associated fibroblasts unique to IBD colon, expressing genes associated with cancer, colitis, and fibrosis, including interleukin-11, also upstream of STAT3." (PMID 37884500, 2023). "Our results suggest JAK inhibitors should be used with caution in cancers driven by pathogenic activation of both NFκB and STAT3 such as CLL." (PMID 37114129, 2023). "In a variety of cancer cells, administration of STAT3 inhibitor was reported to cause massive production of pro-inflammatory cytokines in the peripheral blood of immunocompromised GBM patients by inhibiting the STAT3 activity." (PMID 36923251, 2023). "STAT3 reportedly induces immunosuppression in cancer by upregulating PD-L1 and this overexpression of PD-L1 significantly associates with STAT3 phosphorylation." (PMID 37444518, 2023). "JAK2/STAT3 signaling is aberrantly hyperactivated in various cancers, and such hyperactivation is commonly associated with a poor clinical prognosis." (PMID 36721234, 2023). "It has been demonstrated that loss of STAT5 expression results in cancer development and liver fibrosis due to increased STAT3 activation." (PMID 37369132, 2023). "In particular, persistent STAT3 activation in cancer cells is linked to cell survival, angiogenesis, and metastatic processes, contributing to increased inflammation and tumorigenesis." (PMID 37998389, 2023). "In different cancers, immunosuppression associated with STAT3 activation and STAT3-mediated inhibition of DC function has been reported." (PMID 37047709, 2023). "The analysis showed that the STAT3-ralated genes and proteins mainly acted on pathways in cancer, Th17 cell differentiation, Kaposi sarcoma-associated herpesvirus infection.." (PMID 36977736, 2023).